NUDT10 (nudix hydrolase 10)
Description:
Cleaves a beta-phosphate from the diphosphate groups in PP-InsP5 (diphosphoinositol pentakisphosphate), suggesting that it may play a role in signal transduction. Also able to catalyze the hydrolysis of dinucleoside oligophosphates, with Ap6A and Ap5A being the preferred substrates. The major reaction products are ADP and p4a from Ap6A and ADP and ATP from Ap5A. Also able to hydrolyze 5-phosphoribose 1-diphosphate.
Synonyms: DIPP3-alpha; hDIPP3alpha; APS2; DIPP3A
Tractability: PROTAC: ubiquitination databases record sites on it.
Target class: Enzyme; Hydrolase
Gene: Protein-coding gene on chromosome X (51,332,231 to 51,337,525, forward strand). Ensembl gene ENSG00000122824.
Subcellular location: Cytoplasm
Subcellular location (Human Protein Atlas): Cytosol
Pathways (Reactome):
Metabolism: Synthesis of pyrophosphates in the cytosol
Gene Ontology:
Molecular function: protein binding; bis(5'-adenosyl)-hexaphosphatase activity; bis(5'-adenosyl)-pentaphosphatase activity; diphosphoinositol-polyphosphate diphosphatase activity; endopolyphosphatase activity; hydrolase activity; pyrophosphatase activity
Biological process: adenosine 5'-(hexahydrogen pentaphosphate) catabolic process; diadenosine hexaphosphate catabolic process; diadenosine pentaphosphate catabolic process; diphosphoinositol polyphosphate metabolic process
Cellular component: cytosol; nucleus; cytoplasm
Homologues: Orthologues: macaque NUDT10 (99% identical). Paralogues in human: NUDT11 (99% identical), NUDT4B (90% identical), NUDT4 (90% identical), NUDT3 (74% identical).
Diseases named in the same sentence as NUDT10 in open-access papers:
NUDT10 is named in the same sentence as 21 diseases in open-access papers, as found by Europe PMC text mining. Sharing a sentence is not in itself a finding about the gene and the disease. The quoted sentences say what the papers report.
gastric cancer (4 papers, 2021 to 2025). A primary or metastatic malignant neoplasm involving the stomach. "Nudix hydrolase 10 (NUDT10), located in Xp11.22, increases promoter methylation and is associated with OS in prostate cancer and gastric cancer." (PMID 36732869, 2023). "Similar to our study, a recent study has been concluded that the expressions of NUDT10 mRNA and protein in gastric cancer samples were remarkably reduced than those in controls." (PMID 36118897, 2022). "Firstly, due to the limitation of sample size, our validating result from HPA database is less convincing and more immunohistochemical validation of NUDT10 in gastric cancer are needed." (PMID 34696672, 2021).
prostate carcinoma (4 papers, 2019 to 2023). A carcinoma that arises from epithelial cells of the prostate gland. "A recent study has implicated that low expression of NUDT10 can increase promoter methylation in prostate cancer, exhibiting a tumor suppressor characteristic." (PMID 34696672, 2021). "NUDT10 and Nudix hydrolase 11 (NUDT11) can promote prostate carcinogenesis and increase prostate cancer susceptibility by being involved in a variety of biological processes and mediating cellular stress responses." (PMID 36732869, 2023). "Several genome-wide association studies have indicated that NUDT10, a member of the NUDT family located in Xp11.22, is associated with overall survival in prostate cancer." (PMID 34696672, 2021). "Although expression of nudix hydrolase 10 (NUDT10) has not yet been examined in the context of PCa, the rs5945572 risk SNP within this gene is significantly associated with increased risk of PCa in Caucasian, African, and Asian ethnic groups, functionally implicating this gene in prostate cancer." (PMID 30917865, 2019).
astroblastoma (1 paper, 2025). "The EWSR1(Exon1-7)-NUDT10(Intergenic) fusion is a newly discovered fusion, indicating a novel chromosomal fusion pattern not previously observed in astroblastoma tumours." (PMID 39963393, 2025).
breast carcinoma (1 paper, 2023). "The results showed that 17 m7GRGs were risk factors and significantly impacted breast cancer prognosis, whereas NUDT10, NUDT3, EIF4E3, SNUPN, NUDT16, IFIT5 and EIF3D were favourable prognostic factors." (PMID 37353728, 2023).
colorectal cancer (1 paper, 2025). A primary or metastatic malignant neoplasm that affects the colon or rectum. "We selected NUDT10, a gene that has been relatively understudied in predictive models, to investigate its functional role in colorectal cancer." (PMID 41406096, 2025). "It promotes the occurrence and metastasis of colorectal cancer by maintaining mRNA stability.In contrast, research on NUDT10 is relatively limited." (PMID 41406096, 2025).
colorectal tumor (1 paper, 2025). "Furthermore, the study elucidated the role of NUDT10 in promoting colorectal tumor progression." (PMID 41406096, 2025).
liver cancer (1 paper, 2023). An epithelial or non-epithelial malignant neoplasm that arises from the liver. "Among the genes associated with the prognosis of liver cancer, the genes associated with shorter survival period are AGO2, DCPS, IFIT5, LARP1, NCBP2, NUDT10, and NUDT16; the genes associated with longevity are EIF4E3, EIF4G3, METTL1, NCBP1, NSUN2, NUDT11, NUDT4, and WDR4." (PMID 36845384, 2023).
lymph node metastasis (1 paper, 2021). "High expression of NUDT10 in GC is significantly correlated with lymph node metastasis, TNM stage, and depth of local invasion." (PMID 34696672, 2021). "Furthermore, in our validation cohort, NUDT10 expression was significantly associated with T stage (OR = 3.886, T4 vs. T1+ T2+ T3), lymph node metastasis (OR = 5.133, yes vs. no), and TNM stage (OR = 19, stage III vs. stage I + II)." (PMID 34696672, 2021).
prostate tumors (1 paper, 2019). "Decreased expression of these genes significantly discriminates between recurrent and non-recurrent prostate tumors from the Cancer Genome Atlas (TCGA) cohort (n = 423), and ASB2, NUDT10, and SRPX were significantly correlated with lower recurrence-free survival in patients by Kaplan-Meier analysis." (PMID 30917865, 2019).
tumor (12 papers, 2019 to 2025). "Subsequently, the scratch test further demonstrated that inhibition of NUDT10 impeded the migration of tumor cells." (PMID 41406096, 2025). "Specifically, NUDT11 expression levels were remarkably higher while NUDT10 had remarkably lower levels in tumor tissues." (PMID 36661684, 2022). "We firstly found that high expression of NUDT10 is correlated with advanced tumor stage, deeper local invasion, and worse survival outcomes in patients with GC." (PMID 34696672, 2021). "We determined NUDT10 expression in tumor and adjacent normal samples and paired samples in the TCGA and validation cohorts." (PMID 34696672, 2021). "Under these conditions, although NUDT 10 is highly expressed in tumor tissues, it loses its function in correcting gene alteration, which is consistent with the poor prognosis in the higher NUDT10 subgroup." (PMID 34696672, 2021). "In the TCGA cohort, NUDT10 expression was significantly correlated with tumor grade (P= 0.001), T stage (P< 0.001), and TNM stage (P= 0.002), but was not correlated with age, sex, lymph node metastasis, and distant metastasis." (PMID 34696672, 2021). "The roles of NUDT4 and NUDT10 remain ambiguous in ccRCC tumor progression and metastasis." (PMID 37089261, 2023). "However, the higher expression levels of EIF4E3 and NUDT10 (both p < 0.001) were remarkably in normal tissues than those in tumor samples." (PMID 36118897, 2022). "Considering the roles of the NUDT family and NUDT10 in tumor progression reported in previous studies, we hypothesized that NUDT10 might play an important role in the occurrence and development of GC." (PMID 34696672, 2021). "NUDT10 expression was significantly reduced in tumor tissues compared to normal tissues." (PMID 34696672, 2021). "Interestingly, higher NUDT10 expression was correlated with advanced tumor stage, deeper local invasion, and worse survival outcomes." (PMID 34696672, 2021). "Considering the roles of NUDT family members in tumor progression reported in previous studies, we speculate that NUDT10 might have potential oncogenic peculiarity in GC." (PMID 34696672, 2021). "Only EIF4E3, IFIT5, EIF4G3, NUDT16, NUDT10, NCBP3, and NUDT11 showed decreased expression in tumor tissues." (PMID 41406096, 2025). "Genes such as EIF4E3, IFIT5, EIF4G3, NUDT16, NUDT10, NCBP3, and NUDT11 showed lower expression in tumor tissues, whereas other genes were highly expressed." (PMID 41406096, 2025). "Thus, NUDT10 may have both oncogenic and tumor-suppressive functions in human cancer." (PMID 34696672, 2021). "Other clinical parameters, such as age, sex, grade, and tumor size, were not correlated with NUDT10 expression." (PMID 34696672, 2021). "Methylation of ETNK2, NTN1, and NUDT10 was increased in ERG-fusion negative tumors, which is concordant with the significant loss of TET2 expression in these tumor samples." (PMID 30917865, 2019).
cancer (7 papers, 2017 to 2025). A tumor composed of atypical neoplastic, often pleomorphic cells that invade other tissues. "As a member of the NUDT family, NUDT10 has been reported to promote cell proliferation, suppress apoptosis, and trigger the loss of tumor suppressor genes, which suggest its role as a promoter of cancer development and progression." (PMID 34696672, 2021). "Based on the pharmacogenomic analysis from the CTRP and GDSC databases, we investigated the correlation between NUDT10 mRNA expression and the sensitivity of cancer cells to a broad spectrum of anticancer compounds." (PMID 41406096, 2025). "In both CT26 and MC38 cell lines, the knockdown groups exhibited a decreased proportion of proliferating cells and an increased rate of apoptosis, indicating that inhibition of NUDT10 can suppress the progression of cancer cells." (PMID 41406096, 2025). "To facilitate the clinical transformation of the five genes model, we further identified FDA-approved sensitive drugs that express high levels of CYFIP2, EIF4A1, NUDT1, NUDT4, and NUDT10 in multiple cancer cell types." (PMID 37089261, 2023). "We found 5 primary regulator genes (EIF4E1B, METTL1, NUDT11, NUDT10 and NUDT4B) were differential expressed in more than 15 cancer types." (PMID 36092891, 2022). "The results showed m7G methyltransferases, such as METTL1 and WDR4, were upregulated in a wide range of cancers, while RNA-binding and decapping enzymes (NUDT4, NUDT16, and NUDT10) were significantly downregulated." (PMID 35592316, 2022). "We identified several cancer-related significantly enriched signaling pathways, mainly including ECM interaction and repair of genetic alteration, which are related to high NUDT10 expression in GC." (PMID 34696672, 2021). "Interestingly, we identified NUDT10 and NUDT11 to be essential in all three cancer cell lines." (PMID 29142246, 2017).
NUDT10 also shares sentences with these, for which no sentence is quoted: Clear Cell Renal Cell Carcinoma (1 paper); glioma (1); hepatocellular carcinoma (1); lung squamous cell carcinoma (1); osteosarcoma (1); pancreatic adenocarcinoma (1); thymoma (1); Tinnitus (1); type 1 diabetes mellitus (1); viral infections (1).